SH3TC2 (SH3 domain and tetratricopeptide repeats 2)
Description:
Is involved in nerve myelination and is required for the integrity of nodes of Ranvier (By similarity). It probably functions as a Rab effector in the regulation of endocytic recycling.
Synonyms: KIAA1985; CMT4C; MNMN
Tractability: Antibody: its Gene Ontology location is reachable by antibodies, with medium confidence.
Gene: Protein-coding gene on chromosome 5 (148,923,639 to 149,063,163, reverse strand). Ensembl gene ENSG00000169247.
Subcellular location: Cell membrane; Recycling endosome
Subcellular location (Human Protein Atlas): Cytosol; Nucleoplasm
Gene Ontology:
Molecular function: protein binding
Biological process: regulation of endocytic recycling; regulation of ERBB signaling pathway; regulation of intracellular protein transport
Cellular component: recycling endosome; plasma membrane; cytoplasmic vesicle
Genetic constraint (gnomAD): Loss-of-function variants: 84 observed, 125.85 expected, observed/expected ratio (o/e) 0.67, 90% interval 0.56 to 0.8. The upper end of that interval is the gene's LOEUF score, 0.8, which puts it in group 3 of 6, group 1 being the genes least tolerant of losing a copy. Missense variants: 1,517 observed, 1,630.6 expected, observed/expected ratio (o/e) 0.93, 90% interval 0.89 to 0.97. Synonymous variants: 631 observed, 660.41 expected, observed/expected ratio (o/e) 0.96, 90% interval 0.89 to 1.02.
Homologues: Orthologues: chimpanzee SH3TC2 (99% identical), macaque SH3TC2 (97% identical), rabbit SH3TC2 (87% identical), dog SH3TC2 (87% identical), guinea pig SH3TC2 (85% identical), pig SH3TC2 (84% identical), mouse Sh3tc2 (82% identical), rat Sh3tc2 (81% identical), tropical clawed frog sh3tc2 (45% identical), zebrafish sh3tc2 (41% identical). Paralogues in human: SH3TC1 (35% identical).
Diseases named in the same sentence as SH3TC2 in open-access papers:
SH3TC2 is named in the same sentence as 54 diseases in open-access papers, as found by Europe PMC text mining. Sharing a sentence is not in itself a finding about the gene and the disease. The quoted sentences say what the papers report.
neuropathy (11 papers, 2012 to 2024). A disorder affecting the nervous system that manifests with pain, tingling, numbness, and/or muscle weakness. "It is highly likely that these two SH3TC2 mutations, S1138N and A1090G, are the cause of the neuropathy in our patient confirming that he has CMT4C." (PMID 38707135, 2024). "CMT4C neuropathy, which is caused by mutations in the SH3TC2 gene, is the most common cause of the autosomal recessive form of demyelinating CMT." (PMID 22745917, 2012). "Similarly, mutations in SH3TC2 are associated with Charcot–Marie–Tooth disease, which also confers susceptibility to neuropathies, including CTS75." (PMID 30833571, 2019). "Analysis of the murine model of CMT4C revealed that the capacity of SH3TC2-deficient Schwann cells to properly myelinate underlying axons is affected at the early stages of myelination, which is in line with the early onset of the neuropathy reported in CMT4C patients." (PMID 22745917, 2012). "Hearing loss could develop simultaneously with neuropathy, in some patients with pathogenic variants in PRPS1 (n = 1), NEFL (n = 2), MPZ (n = 1), TRPV4 (n = 1); or at a distance in some cases of variants in SH3TC2 (n = 2) and ABHD12 (n = 1)." (PMID 31393079, 2019). "After establishing an efficient gene replacement method for SH3TC2, we proceeded with a randomized, mock vector-controlled, blinded treatment trial by intrathecal injection in groups of Sh3tc2−/− littermate mice at 3 weeks of age, at early stages of neuropathy." (PMID 30907403, 2019). "Indeed the initial characterization of endogenous SH3TC2 expression in mice revealed high expression specifically in sciatic nerves, localized to Schwann cells, indicating a cell-autonomous loss of function mechanism underlying CMT4C neuropathy." (PMID 30907403, 2019).
scoliosis (6 papers, 2018 to 2023). A congenital or acquired spinal deformity characterized by lateral curvature of the spine. "Mutations in SH3TC2 cause recessive CMT4C usually concurrent with scoliosis, with the onset ranging from infancy to early teens; however, cases with late onset (≤ 30 years) were also reported." (PMID 34193129, 2021). "Numerous mutations in the SH3TC2 gene have been shown to underlie the condition often associated with scoliosis, foot deformities, and reduced nerve conduction velocities." (PMID 30562927, 2018). "Furthermore, patients with SH3TC2 variants also presented with a moderate to severe phenotype, which usually manifested as severe weakness, sensory ataxia and scoliosis." (PMID 37519884, 2023). "Although the pathophysiology of this type of pronounced scoliosis is not fully understood, spinal deformities can be caused by motor deficits in the paravertebral muscles, and the SH3TC2 protein might be involved in spine development." (PMID 33643188, 2021). "Mutations in the SH3TC2 gene cause an autosomal recessive form of CMT4C, which manifests during the second decade of life and is characterized by pronounced scoliosis." (PMID 37372933, 2023). "Biallelic mutations in SH3 domain and tetratricopeptide repeats 2 (SH3TC2) cause Charcot-Marie-Tooth disease type 4C (CMT4C), one of the most common autosomal recessive polyneuropathies associated with early onset, slow disease progression and scoliosis." (PMID 31346473, 2019). "Although most were associated with classic demyelinating phenotypes (55/75, 73.3%), there was considerable phenotypic heterogeneity such as prominent deep sensory disturbances (SH3TC2, PRX) and scoliosis (SH3TC2, MPZ, and PMP22)." (PMID 37519884, 2023). "We summarized phenotypes in the Chinese CMT cohort and concluded that the absence of scoliosis, cranial nerve involvement, or late-onset symptoms does not necessarily preclude SH3TC2 involvement in a given case." (PMID 33643188, 2021).
Charcot-Marie-Tooth disease type 4C (4 papers, 2016 to 2023). "Charcot-Marie-Tooth disease type 4C is the most common recessively inherited demyelinating neuropathy that results from loss of function mutations in the SH3TC2 gene." (PMID 30907403, 2019). "Charcot-Marie-Tooth disease type 4C (CMT4C) is one of the commonest autosomal recessive inherited peripheral neuropathies and is associated with mutations in the Rab11 effector, SH3TC2." (PMID 27068304, 2016).
Charcot-Marie-Tooth neuropathy (3 papers, 2013 to 2020). "Homozygous mutations in the SH3TC2 gene cause autosomal recessive Charcot-Marie-Tooth neuropathy, heterozygous mutations can cause subtle autosomal dominant distal neuropathy." (PMID 28490364, 2017).
acute myeloid leukemia (2 papers, 2022). Acute myeloid leukemia (AML) is a group of neoplasms arising from precursor cells committed to the myeloid cell-line differentiation. "We observed differential expression of SH3TC2 in colon adenocarcinoma (COAD), acute myeloid leukemia (LAML), READ (rectum adenocarcinoma), SKCM (skin cutaneous melanoma), and TGCT (testicular germ cell tumors)." (PMID 35954399, 2022).
Charcot-Marie-Tooth disease (2 papers, 2021 to 2024). An inherited degenerative disorder involving the peripheral nerves. "Homozygous variants in the SH3TC2 gene cause Charcot-Marie-Tooth disease, and cerebellar atrophy has been reported in 20% of patients." (PMID 38587696, 2024). "The “Src homology 3 (SH3) domain and tetratricopeptide repeats 2” (SH3TC2) gene is mutated in individuals with Charcot-Marie-Tooth disease (CMT) and considered relevant to a demyelinating or intermediate subtype of CMT disease, CMT4C." (PMID 33643188, 2021). "Charcot-Marie-Tooth disease (CMT) 4C is one of the most common forms of autosomal recessive (AR) demyelinating neuropathies caused by a mutation in the “Src homology 3 (SH3) domain and tetratricopeptide repeats 2” (SH3TC2) gene." (PMID 33643188, 2021).
colorectal cancer (2 papers, 2022). A primary or metastatic malignant neoplasm that affects the colon or rectum. "We analyzed SH3TC2 in various kinds of cancer to find its tumorigenic role in one or more specific cancers and further explored the mechanism of SH3TC2 in colorectal cancer (CRC)." (PMID 35954399, 2022). "Subsequently, the prognostic role and mechanism of SH3TC2 in colorectal cancer (CRC) were further explored via clinical samples and in vitro and in vivo experiments." (PMID 35954399, 2022). "KEGG analysis depicted that SH3TC2 may participate in the cell cycle, colorectal cancer, DNA replication, mismatch repair, etc.." (PMID 36568637, 2022). "Since both COAD and READ belong to colorectal cancer (CRC) in origin, these results strongly suggest that SH3TC2 may play a key role in the development of CRC." (PMID 36568637, 2022).
demyelinating peripheral neuropathy (2 papers, 2016 to 2024). "In all cases, targeted searches for long deletions were carried out using various methods, including analysis of panel sequencing data and long-range PCR for target patients with specific clinical features of demyelinating polyneuropathies and one pathogenic variant in the SH3TC2 gene." (PMID 38903759, 2024). "Establishing the expression pattern of the endogenous protein is therefore vital both to understand why mutations in SH3TC2 lead specifically to a demyelinating peripheral neuropathy and also to devise potential therapeutic strategies for this and other subtypes of CMT." (PMID 27068304, 2016). "Among 394 patients with demyelinating polyneuropathy in the study group, none had heterozygous pathogenic variants of the SH3TC2 gene." (PMID 38903759, 2024).
gastric cancer (2 papers, 2017 to 2020). A primary or metastatic malignant neoplasm involving the stomach. "The ChIP-seq data obtained from the UCSC genome browser showed that SH3TC2/miR-584 locus is regulated by c-Jun and c-Fos transcription factors, which are known up-regulated oncoproteins in gastric cancer." (PMID 32615958, 2020).
anemia (1 paper, 2019). A reduction in the number of red blood cells, the amount of hemoglobin, and/or the volume of packed red blood cells. "We examined global transcriptome alterations following depletion of DNA replication checkpoint genes (Atr, Mcm4, Mcm5, and Mcm6), the Fanconi anemia gene (Fanca), mRNA processing genes (Snrpal and Snrpd3), and CMT genes (Sh3tc2 and Cmt4b2)." (PMID 31390555, 2019).
Anisocoria (1 paper, 2016). Anisocoria, or unequal pupil size, may represent a benign physiologic variant or a manifestation of disease. "Furthermore, anisocoria [PMP22, MPZ, MFN2, SH3TC2; FYVE, RhoGEF, and PH domain‐containing protein 4 (FGD4) gene], miosis (PMP22, MPZ) and mydriasis (MPZ) have been described previously." (PMID 27088055, 2016).
breast carcinoma (1 paper, 2020). "The adjacent gene miR-584 is located in the first intron of the SH3TC2 gene and was reported to function as a tumor suppressor gene for glioma and clear cell renal cell carcinoma, but to induce migration in breast cancer through TGF-β." (PMID 32637351, 2020).
colon cancer (1 paper, 2022). "We evaluated the expression of SH3TC2 in the clinical stage of colon cancer in gene chip data through the TMNplot database." (PMID 35954399, 2022). "However, higher expression of SH3TC2 in colon cancer, rectal cancer, or CRC did not imply poor prognosis in the overall survival (OS) of cancer patients." (PMID 35954399, 2022).
diffuse large B-cell lymphoma (1 paper, 2020). "In diffuse large B cell lymphoma, SH3TC2 was identified as a signature gene of the poor prognostic CD5+ activated B-cell like (ABC) subtype." (PMID 32637351, 2020).
Kyphoscoliosis (1 paper, 2025). An abnormal curvature of the spine in both a coronal (lateral) and sagittal (back-to-front) plane. "As expected, the striking clinical feature in patients with SH3TC2 variants was the high frequency of kyphoscoliosis, observed in 77% of the patients." (PMID 39776111, 2025).
mesothelioma (1 paper, 2022). A usually malignant and aggressive neoplasm of the mesothelium which is often associated with exposure to asbestos. "Results showed that SH3TC2 expression was independently associated with DFS in four types of cancer, including COAD, mesothelioma (MESO), PAAD, and READ." (PMID 36568637, 2022).
neuroblastoma (1 paper, 2020). Neuroblastoma (NB) is the most common solid, extracranial childhood tumor. "In neuroblastoma, lower SH3TC2 expression level was associated with MYCN amplification and poor survival." (PMID 32637351, 2020).
cancer (5 papers, 2020 to 2023). A tumor composed of atypical neoplastic, often pleomorphic cells that invade other tissues. "Tyrosine kinase-signaling genes, EPHB3, SH3TC2, and GRB7, which are associated with poor disease-free survival and promote cancer progression and invasion, were downregulated by DIM–AHR." (PMID 37834026, 2023). "In the current study, we analyzed the expression level and prognostic value of SH3TC2 in different tumors in the TCGA-GTEx pan-cancer dataset." (PMID 35954399, 2022). "By mining the TCGA database, we found that SH3TC2 in tumor tissue was significantly overexpressed in most cancer types." (PMID 35954399, 2022). "SH3TC2 was shown to be abnormally expressed and significantly associated with disease-free survival (DFS) in many cancers, especially CRC." (PMID 36568637, 2022). "In summary, our study reveals for the first time the expression status and prognostic value of SH3TC2 in pan-cancer and demonstrates the critical role of SH3TC2 in maintaining the cell-cycle progress and growth of CRC." (PMID 36568637, 2022). "The study preliminarily conducted a pan-cancer study of SH3TC2 and further explored the mechanism of SH3TC2 in CRC." (PMID 35954399, 2022). "In our present study, we analyzed the expression of SH3TC2 by using pan-cancer bioinformatic analysis." (PMID 35954399, 2022). "For this, we defined a fold change greater than 1.5 and p value less than 0.05 as a significant difference in SH3TC2 expression between tumor and normal samples in each cancer type." (PMID 36568637, 2022). "To explore the potential role of SH3TC2 in human cancer, we for the first time analyzed the expression landscape of SH3TC2 in 31 cancer types by interrogating the comprehensive cancer database GEPIA." (PMID 36568637, 2022). "But the clinical relevance and biological function of SH3TC2 in human cancer remain largely unclear." (PMID 36568637, 2022). "Patients with each cancer type were divided into high and low expression groups based on the median value of SH3TC2 expression." (PMID 36568637, 2022). "In this study, we for the first time delineated the expression and prognostic landscapes of SH3TC2 in more than 30 cancers." (PMID 36568637, 2022). "Although SH3TC2 expression is prevalent in multiple cancer types and has been recently reported to play an important role in tumorigenesis and tumor progression, its prognostic value and molecular mechanism remain largely unclear." (PMID 35954399, 2022). "Although SH3TC2 expression is prevalent in multiple types of tumors, the function of SH3TC2 in cancer development or therapeutic resistance is less understood." (PMID 32637351, 2020). "We then wondered whether SH3TC2 expression could predict clinical outcomes in any two types of cancer among COAD, PAAD, and READ." (PMID 36568637, 2022). "Given that SH3TC2 is dysregulated in some cancers, we wondered whether SH3TC2 expression could predict patient clinical outcomes." (PMID 36568637, 2022). "The results indicate that SH3TC2 may act as an oncogene or tumor suppressor in different kinds of cancer." (PMID 35954399, 2022). "Thus, our study advances the understanding of SH3TC2's role in pan-cancer and provides a reference for developing SH3TC2 as a clinical biomarker and/or target for CRC." (PMID 36568637, 2022). "Therefore, we used the TISIDB database to comprehensively observe the relationship between SH3TC2 expression and immune cell infiltration in pan-cancer." (PMID 36568637, 2022). "Thus, this study aimed to analyze SH3TC2 in various kinds of cancer to find its tumorigenic role in one or more specific cancers." (PMID 35954399, 2022). "Moreover, the knockdown of SH3TC2 may promote cancer cell apoptosis via multiple molecular mechanisms besides MAPK pathways." (PMID 35954399, 2022).
cancer (continued). "In the present study, we comprehensively explored the expression profile and prognostic value of SH3TC2 in various kinds of solid tumors via the TCGA database and found that SH3TC2 was more highly expressed in multiple cancer types and was closely related to cancer patient survival." (PMID 35954399, 2022). "However, SH3TC2 expression is downregulated in 12 types of cancer." (PMID 35954399, 2022). "The function and mechanism of SH3TC2 in other cancers remain unknown." (PMID 35954399, 2022). "To this end, we used GEPIA database to comprehensively analyze the prognostic significance of SH3TC2 in 33 human cancers, that is, the relationship between SH3TC2 expression and DFS of cancer patients." (PMID 36568637, 2022). "In order to fully investigate the expression status and clinical prognostic value of SH3TC2 in human cancers, we employed the integrated database GEPIA to analyze the expression profile of SH3TC2 in more than 30 types of cancer and its relationship with patient survival." (PMID 36568637, 2022). "SH3 domain and tetrapeptide repeat 2 (SH3TC2) is a protein-encoding gene and has previously been described as a critical signaling hub for neurological disorders, but no systematic analysis of SH3TC2 is available in cancer research." (PMID 35954399, 2022). "Although increasing evidence supports a vital role of SH3TC2 in the tumorigenesis of various kinds of cancer, no systematic analysis of SH3TC2 is available." (PMID 35954399, 2022).
peripheral neuropathy (4 papers, 2016 to 2024). A disorder affecting the peripheral nervous system. "Among the 700 non-related patients referred to our laboratory with a diagnosis of “peripheral neuropathy,” a subset of ten individuals exhibited biallelic pathogenic and likely-pathogenic variants in the SH3TC2 gene." (PMID 38903759, 2024). "Mutation or knockdown of SH3TC2 in mice results in peripheral neuropathy, resulting in decreased motor and sensory nerve conduction velocity and hypomyelination." (PMID 35954399, 2022). "Our expression data help explain why mutations in SH3TC2, previously shown to inhibit Rab11 binding, lead specifically to the demyelinating peripheral neuropathy that characterizes CMT4C." (PMID 27068304, 2016). "Nevertheless, it remains unclear why mutations in SH3TC2 lead exclusively to a demyelinating peripheral neuropathy." (PMID 27068304, 2016). "The exclusive expression of the Sh3tc2 protein in myelinating Schwann cells explains the demyelinating peripheral neuropathy that characterizes CMT4C." (PMID 27068304, 2016).